FOXP3 (forkhead box P3)
Diseases named in the same sentence as FOXP3 in open-access papers (continued):
Sharing a sentence is not in itself a finding about the gene and the disease.
tumor (continued). "Correlations with immune profiles CD4+, CD8+, and FOXP3+ tumor-infiltrating lymphocytes (TILs), tumoral PD-L1, and stem-related factors NANOG and SOX2 were assessed, and also associations with clinical data and patient survival." (PMID 33494389, 2021). "At the same time, TApDCs not only exhibit less production of IFN-α, mainly mediated through tumor-derived TNF-α and TGF-β, but also induce tumor infiltration of ICOS+ Foxp3+ Tregs and drive immunosuppression via ICOS/ICOSL stimulation." (PMID 34737750, 2021). "One of the possible reasons for this finding is that FoxP3+Treg cells suppressed the function of cytotoxic T cells to destroy the function of anti-tumor, which resulted in the escape of immunological surveillance." (PMID 34654443, 2021). "In keeping with these findings, IHC on paraffin-embedded tumor sections showed that puromycin signals overlap with FoxP3 staining." (PMID 34787568, 2021). "For example, FOXP3 is always highly expressed in the tumor environment and is capable of mediating immune escape." (PMID 33575321, 2021). "TCF4 depletion does not impact CD11b+Ly6G+ neutrophils, CD16+CD56+ NK cells, and CD25+FOXP3+ T-reg cells population in the tumor microenvironment of syngeneic CRC liver metastases model." (PMID 34580284, 2021). "Initially, several studies in colorectal cancer patients showed a correlation between tumor-infiltrating Foxp3+ putative Treg cells and a favorable prognosis." (PMID 34407765, 2021). "Further analysis of T cell markers revealed, that the CD4+ helper T cell marker message levels were slightly increased in both tumor types along with the regulatory T cell marker FOXP3." (PMID 35366268, 2021). "Numerous studies have demonstrated that Tregs and FOXP3 are increased in the peripheral blood and tumors of patients with digestive tract malignancies and are positively correlated with tumor stage." (PMID 33838641, 2021). "FOXP3 is the master transcription factor of Tregs, and FOXP3+ T cells are representative TILs that function as tumor suppressors." (PMID 34071550, 2021). "Anti-TNFR2 monotherapy and combinatory therapy significantly reduced the percentage of Foxp3+ Tregs in CD4+ T cells in tumor tissue, with the combination therapy showing a stronger effect." (PMID 34900985, 2021). "In M0, a high expression of FOXP3 + tumor infiltrating lymphocytes (TILs) seemed to prevent at least in part metastases." (PMID 34476575, 2021). "Co-injection of metastatic tumor cells (LMB) with TEMs generated by metastatic tumor EVs significantly increased the number of Foxp3+ T-regs compared to control." (PMID 34298673, 2021). "Foxp3 promotes tumour growth and metastasis by Wnt/β‐catenin activation and inducing epithelial mesenchymal transformation." (PMID 34841705, 2021). "One mechanism of both primary and secondary resistance is the presence of CD4+Foxp3+ regulatory T cells (Tregs) in the tumor microenvironment." (PMID 34676831, 2021). "We assessed some of these subtypes and found that high FOXP3/CD3 ratios and high IL17A tumor levels were associated with worse outcomes." (PMID 33648463, 2021). "CD4+CD25hi Forkhead-Box-Protein P3 (FoxP3)+ Treg cells are frequently found in the course of tumor progression and counteract APC activity, T cell activation, and anti-tumor functions of effector T cells (Teff)." (PMID 33430105, 2021). "The initial view that FoxP3+Treg cells always suppress tumor immunity was challenged in the case of gastrointestinal tumors." (PMID 34654443, 2021). "Foxp3+ Tregs in tumor tissues were positively correlated with CD163+ macrophages (p = 0.011) and CD8+ T cells (p = 0.021)." (PMID 34733785, 2021). "The percentage of CD4+CD25+FoxP3+ Tregs among the total tumor-infiltrated CD4+ cells is 44.45 ± 9.03 in control group as compared to 6.47 ± 1.18 in NIR treated group (P < 0.005; Student’s t-test)." (PMID 33986437, 2021).
tumor (continued). "We did not identify a prognostic trend for FoxP3IM, possibly because cancer cells in the CT produce chemokines, such as CCL22 and CCR4, thus resulting in lower DC infiltration and recruitment of more FoxP3, and consequently favoring tumor growth." (PMID 33710816, 2021). "CCR8 expression was significantly upregulated in the TME of multiple tumor types, always showing a significant (p<0,0001) correlation with FOXP3 expression." (PMID 33589525, 2021). "It has been described that the tumor-suppressor activity of FOXP3 is mediated by the N-terminal region of the protein." (PMID 33671179, 2021). "(B) Fluorescence microscopy of tumor sections from Foxp3-eGFP WT (n = 4) and Cd300a−/− (n = 7) mice, stained with an anti-GFP monoclonal antibody (green) and the DNA-binding dye 4′,6-diamidino-2-phenylindole (DAPI; left)." (PMID 34751648, 2021). "In contrast, high numbers of tumor-infiltrating FoxP3+ cells are related to improved overall survival (OS) in FL." (PMID 34069564, 2021). "The role of Treg cells in CRC seems to be dependent on the co-existence in the tumor tissue and the time of action of different subsets of Foxp3-expressing cells." (PMID 33919941, 2021). "Previously, during the investigation of tumor progression, CTLs were considered as favorable prognostic factors; however, presently, immunosuppressive cells, such as FOXP3+ Tregs and MDSCs, are considered as unfavorable factors affecting patient prognosis." (PMID 33854974, 2021). "Pretreatment biopsies from 64 patients with HNSCC that received ICT were assessed for PD-L1 protein expression and density of CD8+ and FOXP3+ tumor infiltrating lymphocytes (TIL)." (PMID 33923066, 2021). "T regs CD4 + FOXP3 + allow the progression of the tumor by expressing inhibitory factors that inhibit the anti-tumor TH1 response." (PMID 34952631, 2021). "Enhanced CD27 expression on immune cells such as CD8+ and CD4+ T cells residing in the tumor microenvironment, FoxP3-expressing CD4+ T, and CD3−NK1.1+ natural killer (NK) cells augments the activities of these cells." (PMID 32902664, 2021). "On the contrary, the presence of regulatory T lymphocytes (Tregs), characterized by the expression of the Forkhead box P3 (FoxP3) transcription factor, provides tolerance to tumor antigens, thus promotes its development and worsens patient prognosis." (PMID 34117905, 2021). "Accumulating studies have shown that forkhead/ winged-helix transcription factor P3 (FOXP3) infiltrated into tumor tissues plays vital role in tumor immunity." (PMID 34569432, 2021). "The cells responsible for this feature of tumor stroma comprise several macrophage populations (M2), regulatory T-cells (FoxP3+), and myeloid-derived suppressor cells (MDSC)." (PMID 33466316, 2021). "In the future, it would be interesting to evaluate the role of strategies that deplete FOXP3+ cells in the tumor microenvironment." (PMID 34362334, 2021). "Various transplantable tumor models were established in immunocompetent wild-type mice and mice with a Foxp3-specific ablation of Blimp1." (PMID 34798898, 2021). "The evaluation of tumor-infiltrated CD4+CD25+Foxp3+ regulatory T cells designated that treatment of mice with TEXomiR significantly (P = 0.032) decreases the tumor-infiltrated CD4+CD25+Foxp3+ T cells in the TEXomiR group compared with the PBS group." (PMID 33987190, 2021). "The density of FOXP3+ TILs (TILsFOXP3) in ICC tumor samples was 15.7 ± 14.8/field, which is significantly higher than that in para-tumor liver tissues (4.8 ± 5.3/field, P <.001) and lower than CTLA-4 (P <.001)." (PMID 34526987, 2021). "For example, in response to EMT-mediating inflammatory cytokines, the transcription factor Runt-related Transcription Factor 3 (RUNX3) binds to the Forkhead Box P3 (FOXP3) promoter and increases the Treg population within the tumor." (PMID 34830776, 2021).
tumor (continued). "Priming with immunotherapy reduced the number of Foxp3+ cells in the directly-treated tumor compared to thermal ablation alone but marginally increased Foxp3+ cells in the distant tumor." (PMID 33441763, 2021). "Curcumin prevented the tumor-induced infiltration of Foxp3+ Tregs and reduced the stability of Tregs." (PMID 34248973, 2021). "FOXP3, the master regulator of Treg cell differentiation, was used to identify Treg cells in tumor sections." (PMID 34868011, 2021). "In contrast, much lower percentages of CD103+ cells among FoxP3+CD4+ Treg were observed in B16F10E-KO tumours than in B16F10E." (PMID 34471106, 2021). "Immunohistochemical staining for CD4 and Foxp3 was performed to assess the effect of Treg on tumor proliferation." (PMID 33988472, 2021). "The evaluation of the CD4+CD25+Foxp3+ T cells determined that the administration of TEXomiR significantly (p < 0.05) decreased the tumor-infiltrated regulatory T cells compared with the PBS-treated group." (PMID 33987190, 2021). "The current study also supports this theory, in which murine ppp2r1a-deficient tumours exhibit enhanced CD8+ T cell infiltration and reduced Foxp3+ Treg infiltration." (PMID 34911954, 2021). "The unresponsive tumor showed very high level of Foxp3 compared to the responsive tumor and other immunosuppressive markers." (PMID 34479503, 2021). "Controlling tumor-infiltrating CD4+CD25+Foxp3+ Tregs has been considered an essential step for enhancing anticancer immune reactions." (PMID 34064074, 2021). "This is because the accumulation of FOXP3+ occurs together with inflammatory cytokines, possibly implying that Treg cells play a role in repressing tumor inflammation." (PMID 33809974, 2021). "Both BA9 and BT942 reduced the proportion of hCD25+Foxp3+ cells and Foxp3+(Treg) cells in the tumor at early or late phase treatment experiment." (PMID 34824364, 2021). "Tregs represent a critical subset of CD4 T-cells, characterized by CD4 + CD25 + Forkhead box P3+ (FoxP3+) phenotype, able to control peripheral tolerance as well as response to foreign and tumor antigens." (PMID 34640606, 2021). "CD4+ CD25− T cells can be converted into CD4+ CD25high FoxP3+ Tregs after coculture with tumor-derived exosomes." (PMID 34616851, 2021). "CD25+ Foxp3+ Treg cells and Myeloid-derived suppressor cells (MDSCs) are major components in mediating the immune-suppressive tumor microenvironment." (PMID 34282215, 2021). "We first examined the prevalence of tumor-infiltrating Tregs and IL-21+ cells using immunohistochemical staining for FOXP3 and IL-21." (PMID 34026621, 2021). "Our data, on the other hand, consider the potential contribution of TGFβ of tumor origin only, subtracted of the peritumor background, on the tissue enrichment of FoxP3+ cells." (PMID 34769191, 2021). "Subjects treated with pHIFU + ICI had increased levels of CD8+IFNγ+ T cells, increased ratios of CD8+IFNγ+ to CD3+CD4+FoxP3+ and CD11b+Ly6G+ cells, and decreased CD11chigh cells in their tumours compared with controls." (PMID 34229458, 2021). "In genetically engineered mouse models (GEMMs), EGFR-driven tumors express higher levels of PD-L1 with a more immunosuppressive tumor microenvironment (increased FoxP3+ T-cells, decreased CD8+/CD4+ ratio)." (PMID 34488906, 2021). "Future analyses are planned, including characterization of the spatial relationships between effector (CD8+) and suppressive (FoxP3+ or PD-L1+) cell subsets across the various tumor types and correlations with clinical outcomes, such as tumor recurrence." (PMID 33596250, 2021). "Nonetheless, the small amount of cryopreserved tumor tissue used for each experiment enabled efficient enumeration of Tregs by surface markers or intranuclear Foxp3 expression." (PMID 34067849, 2021). "We studied three TIL markers (CD3, CD8 and FOXP3) in various regions within the tumour and in its adjacent environment." (PMID 33640523, 2021).
tumor (continued). "In a mouse model of B16-OVA tumor cells implanted in FoxP3-GFP reporter mice, IDO1 inhibition led to increased IL-17 expression in Tregs cells suggesting that tryptophan and kynurenine metabolism play an important role in Th17/Treg plasticity in vivo." (PMID 33868263, 2021). "A reduction of Foxp3+ was also found in the tumor tissue, together with a reduction of PDL-1, PIK3, and p-AKT and augmented INF-γ levels." (PMID 34200897, 2021). "FOXP3 has been extensively studied in human tumors, which is closely related to tumor immunity, and its correlation with T cells in tumors has recently been reported." (PMID 33747044, 2021). "Another study showed that anlotinib reduced PD-L1 expression on vascular endothelial cells via inactivation of AKT pathway, which then leads to increase in the CD8/FoxP3 ratio in the tumor immune microenvironment." (PMID 34395243, 2021). "Increased numbers of Tregs, and decreased ratios of CD8+ T cells to FoxP3+ Tregs, infiltrating into a tumor are reported to be strongly correlated with poor prognosis in various cancers." (PMID 32203145, 2021). "A high density of tumor-infiltrating Foxp3+ Tregs frequently correlates with improved OS following surgical resection for CRC; thus, Foxp3+ Tregs are regarded as an important prognostic indicator." (PMID 33527196, 2021). "In light of our findings on the strong association between CD30+OX40+ Tregs and CRC, we interrogated subpopulations of tumor-infiltrating Foxp3+ Tregs to identify which ones, if any, correlate with patient survival." (PMID 33527196, 2021). "Tumor T cell suppression commonly results from activation of CD4+/Forkhead box P3 (FoxP3+) T regulatory cells (Tregs) that inhibit effector T cells by various mechanisms." (PMID 34768912, 2021). "Genetic deletion of Ezh2 in Treg cells from tumor-bearing mice reduced FOXP3 expression and modulated their functionality." (PMID 34262562, 2021). "To formally test the function of CCR8 in Treg cell accumulation within tumours, we examined the frequency and number of Foxp3+ Treg cells within MC38 tumours implanted in WT and Ccr8−/− animals." (PMID 33838058, 2021). "An increased number of Foxp3 + Tregs was observed in tumor and peritumoral samples, and increased expression of Foxp3 in tumor-infiltrating Tregs suppressed T cell proliferation and was associated with tumor-node-metastasis stage in GC patients." (PMID 33790881, 2021). "Foxp3+ T cells impair the induction and activation of T cells, thereby compromising tumor killing and promoting tumor progression." (PMID 34758773, 2021). "CD8+ T cells infiltrated the tumor stroma, invasive margin, and center, whereas CD4+ and Foxp3+ T cells mainly infiltrated the tumor stroma and invasive margin." (PMID 35087741, 2021). "Cancer tissues produce large amounts of transforming growth factor beta (TGF-β), which promotes the generation of Foxp3+ Tregs from naïve CD4+ T cells in the local tumor microenvironment." (PMID 34248973, 2021). "Infiltration of both activated CD4+CD69+ T cells and regulatory Foxp3+CD4+ T cells into HNSCC tumor tissue contribute to prognosis." (PMID 33732250, 2021). "IDO expression on tumor cells and CCL-2 secretion from microglia and macrophages in the tumor microenvironment contribute to recruiting Tregs (CD4+CD25+ FOXP3+)." (PMID 34421912, 2021). "We also purified Treg cells from tumor-bearing control or Treg-specific Cd177-KO mice (cKO) and confirmed the similar expression level of FoxP3." (PMID 34599187, 2021). "Vaccination targeting FOXP3 provides an excellent measure for depleting Tregs in anti-tumor immunity." (PMID 34806028, 2021). "Even though many studies evidenced the FOXp3 Tregs are involved in the progression of the tumor, a recent study showed the two different populations of Tregs called FOXp3 low and FOXp3 high have a different role in promoting tumor." (PMID 34303380, 2021).
tumor (continued). "We compared the cell densities of CD8 (+) T cells and FOXP3 (+) T cells in the tumor nest and peri‐tumoral lymphoid stroma between MNT and MNCA cases." (PMID 33819365, 2021). "Tregs are a specialized subset of CD4 T cells, which are identified by the expression of the FOXP3 gene, and are responsible for immune suppression and tumor tolerance by the production of TGF-β and suppression of effector T cells." (PMID 33422072, 2021). "The ultimate fate of the relationship between PD-L1 expression and FOXP3+ T regulatory cells is to rescind effector CD8+ T cell-mediated tumor response ultimately leading to T cell exhaustion." (PMID 33806977, 2021). "In contrast, the median survival duration was 19.2 months (95% CI, 13.8–34.0 months) in patients whose tumours contained FoxP3+ Tregs (p < 0.001)." (PMID 33995529, 2021). "A significant decrease in the number of CD4+ CD25+ Foxp3+ TILs in the tumor site was observed in the liposomal peptide plus CpG-ODN treated group." (PMID 34282215, 2021). "We investigated the associations of FoxP3+ Tregs, IDO+ tumor cells and IDO+ stromal immune cells with tumor stage, prognostic factors and survival in CM." (PMID 34051744, 2021). "scRNASeq analysis of tumor infiltrating T cells revealed that LAIR2 expression co-localized with FOXP3 expressing cells and shared a transcriptional signature with tumor-associated regulatory T (Treg) cells." (PMID 35008369, 2021). "This process results in the recruitment and infiltration of CD3+, CDC4+, CD8+ T cells among tumor tissues and decreases the number of Foxp3+ Tregs." (PMID 33866918, 2021). "Th17-like Tregs that expressed IL-17, IL-22, IL-2, TNF and RORγt but in parallel maintained Foxp3 expression markedly enhanced anti-tumor immunity." (PMID 34539668, 2021). "In contrast, there was a significant increase in the population percentage of CD8+ T (CD3+CD8+) cells, and a significant reduction in the population percentage of Treg cells (CD4+FoxP3+) within the tumor when the mice were treated with PLGA-FAKi (P < 0.05)." (PMID 34112200, 2021). "(C) Flow cytometric analysis of the frequencies of Foxp3+ cells among CD4+ T cells in the tumor (n = 11 in each group) and draining lymph node (n = 8 in each group) in Cd300afl/fl and Cd300afl/fl;ItgaxCre mice." (PMID 34751648, 2021). "This leads to a significant inhibition in tumor growth and increased survival, associated with elevated T cell tumor infiltration and decreased CD4(+) Foxp3(+) T cells." (PMID 34360879, 2021). "HER2 expression and amplification were positively associated with tumor‐infiltrating CXCL13‐positive ICs and CD20‐positive ICs as well as FOXP3‐positive ICs." (PMID 33506656, 2021). "For this reason, all tumor slices stained for CD8α were co-stained for FOXP3 expression and the ratio between the two was assessed within individual mice." (PMID 34253827, 2021). "CD4+ regulatory T (Treg) cells that express the transcription factor Foxp3 are an important T cell subset that are recruited to sites of inflammation and facilitate tumor progression and metastasis in most cancers." (PMID 35008369, 2021). "The increased response to immunotherapy (anti-PD1 and anti-PDL1 antibodies) in this study is associated with the increased functionality of anti-tumor CD8 cells and a trend towards decreased tumor-suppressive FOXP3 T cells with the tumor microenvironment." (PMID 34638488, 2021). "At baseline, MPEs contain a lower frequency of CD4+ and CD4+ regulatory (Foxp3+) T cells compared to matched NSCLC tumor tissue, whereas CD8+ T cells were increased in the MPE compared to tumor samples." (PMID 33987104, 2021). "MECA-79+ TA-HEVs were first observed in mice following various treatments such as adoptive transfer of CD8+ T cells, administration of tumor-targeted LTα or genetic depletion of Foxp3+ regulatory T cells (Tregs)." (PMID 33956259, 2021).